SOCS1 (suppressor of cytokine signaling 1)
Diseases named in the same sentence as SOCS1 in open-access papers (continued):
Sharing a sentence is not in itself a finding about the gene and the disease.
Hodgkins lymphoma (16 papers, 2007 to 2025). A heterogeneous group of malignant lymphoid neoplasms of B-cell origin characterized histologically by the presence of Hodgkin and Reed-Sternberg (HRS) cells in the vast majority of cases. "Somatic loss-of-function mutations in SOCS1 (including 2 mutated residues found in families A and E: P123 and Y1547,8) are frequently observed in B-cell or Hodgkin lymphoma, and are associated with activation of the JAK-STAT pathway in tumor cells." (PMID 33087723, 2020). "For example in Hodgkin lymphoma, a high mutation rate in SOCS1 gene correlates with hyperactivation of JAK2 a gained PD-L1 expression." (PMID 29967604, 2018). "SOCS1 gene has been found to be frequently mutated in both classical Hodgkin lymphoma and primary mediastinal B-cell lymphoma, leading to enhanced signalling by STAT5 and STAT6." (PMID 24757565, 2014). "SOCS1 mutations were also present in 8/19 laser-microdissected Hodgkin and Reed-Sternberg cells of classical Hodgkin lymphomas, which correlated with nuclear accumulation of pSTAT5." (PMID 24757565, 2014). "Mutations of the tumor suppressor gene SOCS-1 (Hs.50640) in classical Hodgkin lymphoma are frequent and associated with nuclear phospho-STAT5 accumulation." (PMID 17559667, 2007). "Lymphoproliferation has also been described as a manifestation of SOCS1 haploinsufficiency, in one case evolving in Hodgkin’s lymphoma." (PMID 41249727, 2025). "Mutations of SOCS1 have been previously shown to be associated with favorable survival in DLBCL and are also frequently detected in Hodgkin lymphoma and primary mediastinal B cell lymphoma (PMBCL), both with a relatively favorable prognosis." (PMID 28302137, 2017). "Mutations in SOCS1 have previously been shown to stabilize p(hospho-) JAK2 in primary mediastinal B- cell lymphoma and boost pSTAT5 stockpiling in Hodgkin lymphoma." (PMID 27144517, 2016). "The JAK/STAT pathway’s negative feedback regulator is SOCS1 (suppressor of cytokine signaling 1): mutations resulting in loss of function of SOCS1, which cause constitutive activation of JAK/STAT signaling, have been reported in both classical Hodgkin lymphomas and B-cell lymphomas." (PMID 38792976, 2024). "Additionally, malignant disease such as Hodgkin’s lymphoma has been observed in one SOCS1+/- patient." (PMID 34421895, 2021). "SOCS1 inactivating mutations or deletions have been previously shown to abolish control of phospho-JAK2 or phospho-STAT5 signaling in primary mediastinal B-cell and Hodgkin lymphomas, recalling the picture described here for JAK3 and SOCS1." (PMID 27144517, 2016). "The third mechanism has been described in Hodgkin lymphomas (classical Hodgkin lymphomas and nodular lymphocyte-predominant Hodgkin lymphomas) and PMBL, in which both high JAK2 expression and p-STAT6 were observed and attributed to SOCS1 mutations via the disruption of a negative feedback loop." (PMID 37835560, 2023).
Obesity (16 papers, 2010 to 2025). Accumulation of substantial excess body fat. "The polymorphism of the SOCS1 gene (rs243330, −1656G>A) is associated with obesity and glucose sensitivity." (PMID 31717271, 2019). "Interestingly, in contrast to NAFLD in a healthy population, the AA genotype of this SOCS1 variant predisposes carriers to obesity." (PMID 31717271, 2019). "Interestingly, SOCS1 has been reported to be upregulated in adipose tissue in two different models of obesity associated with leptin resistance." (PMID 20059770, 2010). "Interestingly, it was also suggested that this SOCS1 variant that affects insulin sensitivity early in life may add to the risk of obesity/higher BMI later in life." (PMID 31717271, 2019). "We also intend to identify the possible association of SOCS1 and SOCS3 transcript levels with metabolic parameters in the context of obesity." (PMID 36609306, 2023). "The study also intended to assess the possible association of SOCS1 and SOCS3 transcript levels with metabolic parameters in the context of obesity." (PMID 36609306, 2023). "Data from in vitro studies and animal models point to the possible role of SOCS1 and SOCS3 in underlying mechanisms pertinent to obesity and associated metabolic disorders." (PMID 36609306, 2023). "Although the current study cannot address the underlying mechanism regarding the role of SOCS1 and SOCS3 in obesity and associated metabolic dysfunction, the possible mechanism can be derived from in vitro and murine model surveys." (PMID 36609306, 2023). "Animal model studies suggest that change in the members of the suppressor of the cytokine signaling (SOCS) family (mainly SOCS1 and SOCS3) is linked to the pathogenesis of obesity-related metabolic disorders." (PMID 36609306, 2023). "In obesity, SOCS1/3 are induced by the chronically increased signaling of pro-inflammatory cytokines, including leptin, via the JAK/STAT pathway." (PMID 35406000, 2022). "In obesity, the insulin and leptin resistance occurring in immune cells can be traced to an increased SOCS1/3." (PMID 35406000, 2022). "Obesity and inflammatory cytokines increase ubiquitin ligase SOCS1/3 and MG53, thereby decreasing IRS-1/2 levels." (PMID 26074875, 2015). "Furthermore, as one of the target mRNAs, suppressor of cytokine signaling 1(Socs1) is a key part of obesity-induced inflammation and plays a critical role in IR." (PMID 40070461, 2025). "However, in obesity, chronically elevated leptin levels induce SOCS1 and SOCS3, which in turn inhibit JAK2 phosphorylation and downstream STAT1/STAT2 activation." (PMID 40844207, 2025). "It was found that unlike SOCS3, which disclosed an elevating expression pattern, the expression level of SOCS1 was lower in the women with obesity as compared with their non‐obese counterparts (P-value = 0.03 for SOCS1 transcript level and P-value = 0.011 for SOCS3 transcript level)." (PMID 36609306, 2023). "Similarly, decreased levels of Cebpb, Pparg, and Socs1 mitigated diet-induced obesity." (PMID 30369883, 2018). "Our study suggests that miR-221-3p led to the development of IR in adipocytes and mice with obesity, at least partially, by targeting the 3′-UTR of SOCS1." (PMID 41002956, 2025). "Among SOCS family members SOCS1 and SOCS3 have received special attention in the pathogenesis of different disorders like immune disorders, tumorigenesis, type 2 diabetes, and obesity." (PMID 36609306, 2023). "Although the current study as a preliminary one opens an avenue to the involvement of SOCS1 and SOCS3 in the obesity etiology, however, several limitations merit comment." (PMID 36609306, 2023). "Ueki demonstrated in a mouse model that in both obesity and lipopolysaccharide (LPS)-induced endotoxemia there is an increase in SOCS proteins, SOCS1 and SOCS3, in the liver." (PMID 37511764, 2023).
Obesity (continued). "After bisulfite treatment of DNA, methylation-specific PCR was used to assess the putative methylation of 10 CpG sites in the promoter of SOCS1 and 13 CpG sites in SOCS3 in SAT from women with obesity and normal weight." (PMID 36609306, 2023). "Notably, SOCS1 and SOCS3 dysregulation intersect with host comorbidities such as obesity, type 2 diabetes, and metabolic syndrome, all of which are strongly associated with increased COVID‐19 severity and mortality." (PMID 40844207, 2025). "Our results showed that neither SOCS1 methylation level nor SOCS3 methylation level alter in SAT women with obesity in comparison with ones with normal weight." (PMID 36609306, 2023). "In line with our data, increased basal transcript levels of SOCS3 but not SOCS1 were found in peripheral blood mononuclear cells of individuals with obesity as compared with their non-obese counterparts." (PMID 36609306, 2023). "SOCS1/3 and E3 ligase MG53 expression, also known as TRIM72, were elevated by inflammation and obesity, which may induce insulin resistance in adipose tissue, liver, and skeletal muscle." (PMID 26074875, 2015). "Notably, the miR-221-3p/SOCS1 axis has not been previously investigated in the context of obesity-induced IR, making this the primary focus of our research." (PMID 41002956, 2025). "Interestingly, all tissues of T2D patients showed altered expression of genes involved in the inflammation response—such as SOCS1 in WB; CCL20 and SLAMF1 in SAT; ACP5, FOS, and JUN in VAT; and PLA2G2A in LT, showing the relevance of the systemic chronic inflammation in obesity and T2D." (PMID 29466957, 2018). "Our findings point to alterations of SOCS1 and SOCS3 transcript levels, but not promoter methylation levels in subcutaneous adipose tissues from women with obesity." (PMID 36609306, 2023). "As for the analysis of promoter methylation, it was found that SOCS1 and SOCS3 methylation were not significantly different between the individuals with obesity and normal weight (P-value = 0.45 and P-value = 0.89)." (PMID 36609306, 2023). "As for the analysis of promoter methylation, it was found that SOCS1 (P-value = 0.45 and Z-score = -0.78) and SOCS3 methylation (P-value = 0.89 and Z-score = -0.156) were not significantly different between the individuals with obesity and normal-weight." (PMID 36609306, 2023).
cervical carcinoma (15 papers, 2014 to 2026). A carcinoma arising from either the exocervical squamous epithelium or the endocervical glandular epithelium. "In precancerous lesions and different stages of cervical cancer, an undetectable or reduced expression of SOCS1 was reported compared to the expression in the normal cervix." (PMID 37372319, 2023). "SOCS1 is hypermethylated in cervical cancer and renewal of its expression upsurges Rb protein thereby inhibits cell proliferation." (PMID 35096000, 2021). "A decrease in the expression of SOCS1 has also been observed in precancerous lesions and in the different stages of cervical cancer; this decrease in the expression of SOCS1 apparently correlates with the severity of the lesion." (PMID 33076315, 2020). "SOCS1 is hypermethylated in cervical cancer; restoration of its expression, increases Rb protein and suppresses cell proliferation." (PMID 31766427, 2019). "All cervical cancer cell lines tested showed lower expression of SOCS1, SOCS3, and SOCS5 than normal tissue or cell lines." (PMID 25849377, 2015). "However, they also show that overexpression of SOCS1 or SOCS3 confers radioresistance to cervical cancer cells." (PMID 37372319, 2023). "Wild-type cervical cancer cell lines showed repressed expression of SOCS1, SOCS3, and SOCS5." (PMID 25849377, 2015). "Studies have shown that miR-29a targets several mRNAs in cervical cancer, such as NAD-dependent deacetylase sirtuin-1 (SIRT1), cell division regulatory protein 42 isoform (CDC42), and suppressor of cytokine signaling-1 (SOCS1)." (PMID 39590348, 2024). "Later, in 2015, Kim’s group analyzed SOCS1, SOCS3, and SOCS5 in cervical cancer samples and HPV+ cervical cancer cell lines; they found that the expression of these three SOCS proteins decreased compared to tissues from the normal cervix." (PMID 37372319, 2023). "Ectopic expression of SOCS1 or SOCS3 conferred radioresistance to HeLa cells, which implied SOCS signaling regulates the response to radiation in cervical cancer." (PMID 25849377, 2015). "SOCS1, SOCS3, and SOCS5 expression was lower in cervix cancer than surrounding normal tissue, and the mRNA levels of SOCS genes were lower in cervical cancer cell lines than in normal cervix tissue or fibroblast cell lines." (PMID 25849377, 2015). "We show that altered SOCS1 and SOCS3 expression may contribute to the radiosensitive phenotype in cervical cancer." (PMID 25849377, 2015). "All these results led to the conclusion that SOCS1, SOCS3, and SOCS5 expression ishigher in normal tissue than in cervical cancer, and support the possibility that downregulation of SOCS might contribute to the tumorigenesis or maintenance of cervical cancer." (PMID 25849377, 2015).
lung carcinoma (15 papers, 2013 to 2025). "The purpose of this study was to compare the expression of SOCS1 in plasma samples from normal participants and patients with lung cancer and to evaluate its association with survival." (PMID 38521953, 2024). "Among these genes, overexpression of the Suppressor of Cytokine Signaling 1 (SOCS1) was notably associated with poor survival of lung cancer patients." (PMID 37916165, 2023). "Additionally, the survival curves of patients with lung cancer using Kaplan-Meier (KM) plot analysis showed that low SOCS1 expression was associated with poor prognosis." (PMID 38521953, 2024). "Furthermore, high expression of SOCS1 was associated with resistance to CDDP in the lung cancer cell lines employed." (PMID 37916165, 2023). "SOCS1 protein was also significantly higher in A549 cells after TAP2 downregulation and the expression of TAP2 reduced SOCS1 protein levels in lung cancer cells supporting a bi-directional modulation." (PMID 40091029, 2025). "Upon uptake by lung cancer cells, miR-210-3p targets the SOCS1 gene, activating the STAT3 pathway by suppressing SOCS1 expression, thereby enhancing VEGF production." (PMID 39273095, 2024). "Further studies are needed to evaluate the effect of SOCS1 expression on combining conventional therapies with immunotherapy or immunotherapy combinations, particularly in lung cancer." (PMID 39596207, 2024). "As a result, we confirmed that the mRNA expression of SOCS1 was decreased in plasma of patients with lung cancer compared to that in the normal group." (PMID 38521953, 2024). "Second, in future studies, the overexpression of SOCS1 in these cells and the prognostic significance of SOCS1 in lung cancer patients should also be assessed." (PMID 35789603, 2022). "Suppressor of cytokine signaling 1 (SOCS1) can significantly induce apoptosis and suppress the growth of lung cancer cells." (PMID 27811366, 2016). "Promotes EMT and enhances lung cancer progression by downregulating SOCS1 and SHIP1." (PMID 40895189, 2025). "Our study revealed that miR-6794-5p inhibits SOCS1 expression at the cellular level by directly binding to it and confirmed that SOCS1 was expressed at a lower level in plasma samples from patients with lung cancer than in normal groups." (PMID 38521953, 2024). "Notably, the 3B1A and NCI-H1573 cell lines derived from advanced stages of lung cancer showed high levels of SOCS1, whereas the A-549 and NCI-H1437 cell lines expressed barely detectable or minimal levels of SOCS1." (PMID 39596207, 2024). "Silencing of TAP2 in lung cancer cells altered key intracellular immunomodulatory pathways, limited sensitivity to proinflammatory cytokines, reduced the levels of surface peptide-HLA complexes and protected malignant cells from tumor antigen-specific T-cell killing via SOCS1 upregulation." (PMID 40091029, 2025). "Comparable responses in TAP2, SOCS1 levels and surface peptide-HLA complexes after IL-4 treatment were observed in PC9 lung cancer cells." (PMID 40091029, 2025). "In addition, a low level of suppressors of cytokine signaling (SOCS)-1/3, a Janus kinase (JAK) inhibitor, was observed in lung cancer cells and its transfection decreased CFH protein levels and promoter activity." (PMID 30987235, 2019). "First, we assessed the levels of SOCS1 using treatments and no treatment in the lung cancer cells." (PMID 35789603, 2022). "In conclusion, our results highlighted that CFH overexpression in lung cancer is due to the demethylation of the STAT4 regulatory region, resulting in its over expression, which may be activated by the JAK/STAT pathway negatively controlled by SOCS-1 proteins." (PMID 30987235, 2019).
COVID-19 (13 papers, 2020 to 2025). A disease caused by infection with severe acute respiratory syndrome coronavirus 2. "We suggest in this Perspective that SOCS1/3 antagonist is a simple counter measure to SOCS1/3 and should be an effective mechanism as a prophylactic and/or therapeutic against the COVID-19 pandemic that is caused by coronavirus SARS-CoV2." (PMID 33193390, 2020). "It has been found that miR-155 is relatively upregulated in the PBMCs of COVID-19 patients and negatively correlated with SOCS-1 expression." (PMID 38006062, 2023). "Higher SOCS-1 expression in COVID-19 patients correlates with SARS-CoV-2’s greater pathogenicity compared to the influenza A virus." (PMID 36298646, 2022). "Considering the role of SOC1 as a modulator of anti-viral responses, evidence of down-regulated SOCS1 expression by the overexpression of miR-155-5p in patients with COVID-19 observed in the present study is noteworthy." (PMID 35885930, 2022). "We found a negative correlation between the relative expression of miR-155-5p and SOCS1 during different stages of the COVID-19 course." (PMID 35885930, 2022). "We also highlighted a significant time-dependent change in miR-155-5p and SOCS1 levels during COVID-19." (PMID 35885930, 2022). "The discussion here addresses the potential downside of SOCS1/3 antagonist as virus inhibitor, with potential exacerbation of the inflammatory condition that drives severe COVID-19." (PMID 33193390, 2020). "We determined the association between LTBi positivity with severity of COVID-19 as well as mRNA expression of immune related genes including those required for MTB as well as SARS-CoV-2 control; IFN-γ, IFN-α, IL-6, IL-10, OAS1, MAVS, SOCS1 and SOCS3 molecules." (PMID 41468475, 2025). "Our results support that host miR-155-5p and SOCS1 may indeed play a role in the prognosis of COVID-19." (PMID 35885930, 2022). "A reasonable question pertaining to the SOCS1/3 antagonist is whether it would exacerbate the cytokine storm and other hyperimmune aspects of COVID-19, particularly so as there are considerable efforts to improve disease outcomes by anti-inflammatory and anti-clotting approaches." (PMID 33193390, 2020). "In contrast, the expression levels of SOCS1 and IFNG remained stable throughout the hospital stay in patients with severe COVID-19." (PMID 40927375, 2025). "Whilst mRNA levels of IFN- γ, IFN-1α, MAVS, IL-6, SOCS1 and SOCS3 were similar between LTBi positive individuals in the HC and COVID-19 groups." (PMID 41468475, 2025). "In individuals with severe or critical COVID-19, a functional interaction of the TYK2 receptor subunit with the suppressor of cytokine signaling 1 (SOCS1) and SOCS3 has also been documented." (PMID 38741892, 2024). "Given the current circumstances of empirical rather than mechanistic approaches to treating COVID-19, focus on SOCS1/3 would seem both reasonable and rational." (PMID 33193390, 2020). "Thus, the precise role of MALAT1 and SOCS-1, whether as a potential therapeutic target of ALI/ARDS, a regulator of inflammation, or a biomarker in COVID-19, needs to be deciphered." (PMID 35807375, 2022). "Furthermore, it determined four possible therapeutic targets that increase the Th1 compartment in severe COVID-19: the activation of the IFN-γ pathway, or the inhibition of TGF-β or IL-10 pathways or SOCS1 protein; from these, inhibiting SOCS1 has the lowest number of predicted collateral effects." (PMID 36678366, 2022).